SMAD4 (SMAD family member 4)
Diseases named in the same sentence as SMAD4 in open-access papers (continued):
Sharing a sentence is not in itself a finding about the gene and the disease.
adenoma (continued). "Differential enrichment in stem cell clusters was observed between the two genotypes, consisting of 61.8% of the total cell population in Smad4fl/fl adenoma compared to 47.3% in Smad4+/+." (PMID 40348815, 2025). "For example, 35 DEGs were observed in Smad4Δ/Δ compared to 689 in Smad4+/+ adenomas at t = 12 h vs t = 0 h." (PMID 40348815, 2025). "A Pak3High cluster (Pak3; P21 Rac1/CDC42 activated kinase 3) was the most enriched in Smad4fl/fl (10.5%) compared to Smad4+/+ (2.5%) control adenoma." (PMID 40348815, 2025). "Pathway enrichment analysis using tmod also showed that E2f., G2m, Myc and mTORC targets were more significantly downregulated in Smad4+/+ adenomas compared to Smad4Δ/Δ adenomas." (PMID 40348815, 2025). "Subsequently, the late stage adenoma shows loss of 18q-arm, where it maps the best candidate tumor suppressor gene DPC4/MADH4, which encodes SMAD4, involved in the TGF-β pathway." (PMID 25883651, 2015). "First, SMAD4 alteration contributes to human colorectal tumorigenesis at a relatively early stage, late adenoma formation." (PMID 20707908, 2010). "We use the human adenoma cell line LT97 carrying mutations of the APC and Ki-ras genes as a model for early stage premalignant tumor cells with intact Smad4." (PMID 20307265, 2010). "Because the mouse tumors are adenomas, we would like to know if SMAD4 is altered or intact in these tumors." (PMID 20707908, 2010). "In addition, TGF-β1 exposure resulted in a 0.25 log2FC reduction in Survivin (Birc5) expression after 12 h in Smad4Δ/Δ compared to a 2.55 log2FC reduction in Smad4+/+ adenoma." (PMID 40348815, 2025). "In parallel, loss of SMAD4, located at 18q21 or sometimes 14q22 depending on cytogenetic context, impairs TGF-β–mediated growth inhibition and is frequently observed in advanced adenomas or intramucosal carcinomas." (PMID 40919165, 2025). "Smad4+/+ adenomas were more sensitive to TGF-β1, with an IC50 of 24 pM and threshold of 0.39 pM." (PMID 40348815, 2025). "Time series analysis using the likelihood ratios showed differences in expression of genes including Fos, Lama3, Aldh1a3, Col7a1 and Doks associated with increased induction by t = 12 h, whereas E2f8, Exo1, Clspn, Kif14 and Kif12 all were decreased in Smad4+/+ adenomas." (PMID 40348815, 2025). "Under the same conditions, no nuclear localisation of Smad4 (43 kDa) was detected in Smad4Δ/Δ adenomas, consistent with loss of DNA binding function." (PMID 40348815, 2025). "To assess the transcriptome response to TGF-β1 that might inform differences between Smad4+/+ and Smad4Δ/Δ adenoma organoids, bulk paired-end RNA-seq detected 16,143 gene transcripts that we utilised for the analysis of differentially expressed genes (DEG)." (PMID 40348815, 2025).
adenoma (continued). "Smad4 protein was clearly detected in ApcΔ/ΔSmad4+/+ adenoma and adjacent tissue as expected." (PMID 40348815, 2025). "Next, the progression of these cells into late adenoma and colorectal adenocarcinoma is caused by mutations in other factors, such as transforming growth factor beta (TGF-β), cell division control protein 4 (CDC4), and SMAD family member 4 (SMAD4)." (PMID 36496998, 2022). "Furthermore, down-regulation of the differentiation-promoting transcription factor SMAD family member 4 (SMAD4) in vivo resulted in WNT-mediated adenoma formation in differentiated mouse intestinal tissue." (PMID 35954376, 2022). "The observed difference suggests that the mechanisms causing SMAD4 mutations in CRC and polyp are somewhat distinct from each other, or maybe conversion and transition of adenoma into early carcinoma needs different engines." (PMID 35154600, 2021). "Similarly, blocking stromal BMP4 signals in epithelial cells leads to adenoma-like lesions and deletion of murine Smad4 in T cells results in GI cancer." (PMID 30783098, 2019). "To exclude whether there may have been a genotype dependent difference in the floxing efficiency between Apc and Smad4 that may have accounted for the two-fold differences in growth in culture, we also generated adenoma with an alternative conditional Cre (Villin-CreERT2)." (PMID 40348815, 2025). "Together, these results credential this model as reflective of the importance of SMAD4 in the adenoma to carcinoma transition and support additional experimentation in future studies to determine whether a single event is responsible for simultaneous Apc and Smad4 loss in AKP mice." (PMID 41051921, 2025). "Thus, adenoma Smad4 specific alteration in genes expression may indirectly alter the inflammatory and innate immune environment." (PMID 40348815, 2025). "However, it is not in agreement with the previous notion that SMAD4 mutations rarely occurred either in adenoma or intramucosal carcinoma, but was common in advanced CRCs." (PMID 28179590, 2017).
adenoma (continued). "For subsequent experiments, a TGF-β1 concentration of 390 pM was used to differentiate the TGF-β1 context-dependent sensitivity effects between Smad4+/+ (100 fold higher than the threshold) and Smad4Δ/Δ (at threshold but below IC50) adenomas." (PMID 40348815, 2025). "SMAD3, SMAD4, and CEBPB came up as key transcription factors regulating cancer progression at the late adenoma stage." (PMID 36499586, 2022). "The results also included previously unreported genes including AKT3, NCOR2, PIK3R2, SMAD4, and TGFBR1, from which AKT3 and PIK3R2 were present in the early adenoma stage and SMAD4 and TGFBR1 were present at the late adenoma stage." (PMID 36499586, 2022). "These genes were involved in different stages of cancer development as analyzed using the KEGG pathway, this includes SMAD4 and TGFBR1 at the late adenoma, and AKT3 and PIK3R2 at the carcinoma stage in CRC development." (PMID 36499586, 2022). "Further, the tumor suppressor genes, SMAD2, SMAD4, and BAX, were also involved in the late adenoma stage." (PMID 36499586, 2022). "Paraffin-embedded tissues of adenomas from FAP patients (n=6) and adenocarcinomas from CRC patients (n=9) were stained for Smad4." (PMID 33424832, 2020). "In colorectal tumors with an intact adenoma-carcinoma zone, PTEN and SMAD4 frequently show an inverse alternating expression pattern in this transition." (PMID 26098881, 2015). "Responses of Smad4-reexpressing cancer cells were compared to responses of LT97 cells, a cell line derived from a late adenoma and carrying inactivated APC as well as an activated Ki-ras oncogene." (PMID 20307265, 2010). "The adenoma burden in heterozygote Apcfl/flSmad4+/flLgr5-CreERT2 compared to controls was statistically non-significant and does not support either Smad4 haplo-insufficiency or a dominant negative effect of Smad4fl/+." (PMID 40348815, 2025). "Adenoma from ApcΔ/ΔSmad4Δ/Δ did not label strongly with anti-Smad4 antibodies, consistent with adenoma-specific disruption in both the small and large intestine." (PMID 40348815, 2025). "SB-505124, a TGF-βR1 small molecule inhibitor also had no significant inhibitory effect on Smad4+/+ and Smad4Δ/Δ adenoma growth (1 μM) without the exogenous addition of TGF-β1." (PMID 40348815, 2025). "Here, we used murine conditional Apc dependent intestinal models to generate in vivo and in vitro adenoma with and without Smad4 pathway modification to prospectively identify phenotypes and context specific gene expression." (PMID 40348815, 2025). "Among the seven upregulated genes the expression levels of which were over five times higher than those in the matched normal tissues, the expression levels of IGF-2, E1AF, iNOS, nm23, Smad4, and TIMP-1 genes were significantly higher in the early invasive carcinoma group than in the adenoma group." (PMID 15785755, 2005).
adenoma (continued). "Overall, adenoma Smad4 LOF may stimulate the conditions for increased local TGF-β1 ligand supply and further stimulation of the pathway, contributing to differentiation arrest, chronic inflammation and subsequent adenoma progression." (PMID 40348815, 2025).
liver fibrosis (52 papers, 2013 to 2026). "This study reveals the critical role of SUMOylation modification in CE-associated hepatic fibrosis and elucidates a novel anti-fibrotic mechanism whereby GA targets the SUMOylation-Smad4 axis to regulate the immune microenvironment." (PMID 41529030, 2026). "We previously demonstrated that Smad4 deficiency in hepatocytes alleviated CCl4-treated liver fibrosis." (PMID 39346534, 2024). "Since HSCs activation is a major event in the pathogenesis of liver fibrosis, we further explored the underlying mechanism by which Smad4 expression in hepatocytes affected the activation of HSCs." (PMID 36232998, 2022). "Since the genes of Smad4, Jun, Ctnnb1, and Smad5 have been reported to be associated with liver fibrosis, and the Notch2 gene was considered to be related to Wnt and TGF-β signaling pathways, these five candidate target genes were selected for research." (PMID 35883205, 2022). "A similar study found that the high expression of Smad-2 and Smad-4 was associated with liver fibrosis in rats using in situ hybridization." (PMID 28086769, 2017). "Additionally, CHE interfered with the expression of TGF-β1, Smad4, and Smad7 proteins, further confirming its inhibitory effect on hepatic fibrosis in mice, associated with the TGF-β/Smads signaling pathway." (PMID 39239653, 2024). "TGF-β1/Smad4 regulated collagen deposition is a hallmark of hepatic fibrosis." (PMID 36482069, 2022). "This study reveals that SUMOylation of Smad4 regulates the M2 polarization of macrophages and the crosstalk between macrophages and HSCs, thereby promoting the progression of hepatic fibrosis mediated by E.granulosus infection." (PMID 41529030, 2026). "Our previous study demonstrated that the targeted knockout of Smad4 in hepatocytes attenuates hepatic inflammatory cell infiltration and fibrosis during the progression of CCl4 induced liver fibrosis." (PMID 39890803, 2025). "Some studies have also revealed that miR-122 can improve liver fibrosis by reducing the expression of decapentaplegic protein 4 (Smad4), a primary protein in the TGF-β1 signaling pathway, and limiting collagen production in HSCs." (PMID 41244150, 2025). "miR-455–3p can also suppress the activation of hepatic stem cells (HSCs) and liver fibrosis by downregulating the heat shock protein (HSP) 47/TGF-β/Smad4 signaling pathway." (PMID 41244150, 2025). "Exosomes from BMSCs with miR-148a-5p mitigated liver fibrosis in a mouse model by downregulating Smad4 in stellate cells, as confirmed by reduced TGF-β1 and tissue inhibitor of metalloproteinase 1 (TIMP-1)." (PMID 40676634, 2025). "We constructed a mouse model with the hepatocyte-specific knockout of SMAD4 gene (SMAD4Δhep) and induced liver fibrosis using CCL4, and found that the expression of SMAD4 was significantly enhanced in the fibrotic liver compared to normal liver tissue." (PMID 38385079, 2024). "A recent study revealed decreased XPO4 hepatic expression with advancement of liver fibrosis through regulation of transforming growth factor beta (TGF-β)/SMAD3/SMAD4 -mediated HSC activation." (PMID 38722973, 2024). "We recently found that Smad4 deletion in hepatocytes alleviates liver fibrosis via the p38/p65 pathway." (PMID 39346534, 2024). "In this study, FMGs inhibited TGF-β1 and Smad4 expression while increasing Smad7 expression in the injured rat liver, demonstrating their efficacy in treating liver fibrosis." (PMID 39195542, 2024). "In contrast to the results of this study, the expression of Smad4 was increased in TAA-induced hepatic fibrosis in mice and then alleviated by silymarin." (PMID 38637422, 2024). "Our results showed that Smad4 deletion in hepatocytes decreased CCl4-induced liver fibrosis by regulating the expression of inhibitor of differentiation 1 (ID1) and the secretion of connective tissue growth factor (CTGF) in hepatocytes." (PMID 36232998, 2022).